KMO (kynurenine 3-monooxygenase)
Diseases named in the same sentence as KMO in open-access papers (continued):
Sharing a sentence is not in itself a finding about the gene and the disease.
glioma (6 papers, 2014 to 2025). A benign or malignant brain and spinal cord tumor that arises from glial cells (astrocytes, oligodendrocytes, ependymal cells). "In recent years, the importance of other components of the KP downstream IDO and TDO have been studied on different cancer models including gliomas, where the expression of other enzymes such as KMO has been reported." (PMID 36355137, 2022). "Higher KMO mRNA expression was observed in glioma samples than in patients diagnosed with only a neurological disease; high KMO mRNA expression was also observed when using samples from patients with GBM in the TCGA program." (PMID 34440798, 2021). "KYNU and KMO were recognized as hazardous factors in previous and our studies, indicating that upregulated tryptophan catabolism and low concentration of tryptophan would lead to worse prognosis in gliomas." (PMID 36386216, 2022). "This change in KMO expression could be a consequence of the de-differentiation process described in glioma models that involves differentiated malignant cells gaining plasticity." (PMID 34440798, 2021). "This study showed for the first time that KMO expression and activity are present in glioma cells." (PMID 34440798, 2021). "However in contrast, both KYNU and KMO expression was significantly lower in stimulated and unstimulated glioma cells compared to stimulated AA and unstimulated HFA, respectively." (PMID 25415278, 2014). "Inhibiting KYNU and KMO may represent a novel therapeutic approach for the treatment of glioma." (PMID 25415278, 2014). "Among the most strongly decreased candidates, we observed proteins related to DNA repair (FANCA, USP38, NET1), autophagy (BCAS3), cancer cell migration and/or invasion (RASSF2, KMO, BCAS3), as well as proteins that can be generally considered as pro-tumorigenic, particularly in glioma (KMO, BCAS3)." (PMID 39833546, 2025). "Up-regulation of both KMO and KYNU in glioma may lead to increased production of 3-HK and 3-HAA, which may contribute to creating an immunosuppressive micromilieu by accumulating tryptophan toxic metabolites." (PMID 25415278, 2014).
Stroke (6 papers, 2019 to 2025). Sudden impairment of blood flow to a part of the brain due to occlusion or rupture of an artery to the brain. "KP dysregulation, including an increase in KMO activity, is associated with numerous pathological presentations, including neurological disorders, autoimmune diseases, inflammation, cancer, and stroke." (PMID 36290320, 2022). "In stroke research, KMO has been shown to inhibit mitochondrial autophagy, facilitating brain repair following a stroke." (PMID 41170198, 2025). "Overexpression of KMO eliminated the beneficial effect of circSCMH1 administration on behavioral recovery at different time points after stroke as measured by various behavioral tests." (PMID 40699861, 2025). "The conclusion is made that the novel mechanism by which circSCMH1 downregulates KMO expression was revealed and that such role of circSCMH1 in promoting stroke recovery makes it a therapeutic target for the treatment of ischemic stroke." (PMID 40699861, 2025). "Our findings thus revealed that circSCMH1 was able to enhance functional recovery via KMO-regulated mitophagy, providing a previously overlooked mechanism through which circSCMH1 promotes stroke recovery." (PMID 39659575, 2024). "Together, our results indicated that circSCMH1 plays a role in post-stroke repair by inhibiting KMO-mediated mitophagy." (PMID 39659575, 2024). "We further elucidated the specific mechanism by which KMO regulates functional recovery following stroke, underscoring a novel mitochondrial role for KMO." (PMID 39659575, 2024). "Taken together, the findings of this study highlight the functional link between KMO and functional recovery after stroke: The overexpression of KMO was able to promote mitophagy and aggravate post-stroke injury." (PMID 39659575, 2024). "Moreover, circSCMH1 affected neuroplasticity and vascular repair after stroke through the regulation of KMO expression." (PMID 39659575, 2024). "CircSCMH1 was found to promote functional recovery after stroke by regulating KMO expression, which was independent of KMO enzymatic activity." (PMID 39659575, 2024). "However, we found that treatment with circSCMH1 did not affect the concentration of 3-HK after stroke, suggesting that the post-stroke repair function of circSCMH1 was independent of KMO catalytic activity." (PMID 39659575, 2024).
acute kidney injury (5 papers, 2019 to 2024). Sudden and sustained deterioration of the kidney function characterized by decreased glomerular filtration rate, increased serum creatinine or oliguria. "Efforts to inhibit the release of kynurenine-3-monooxygenase have been shown to reduce 3-hydroxykynurenine levels to alleviate acute kidney injury, prevent multiple organ failure, and ameliorate histological changes in lung tissue that are consistent with ARDS." (PMID 36290606, 2022). "Diminished de novo NAD+ formation due to KMO downregulation in proximal tubular epithelial cells was postulated as one of the potential mechanisms of acute kidney injury (AKI)." (PMID 39337426, 2024).
autoimmune disease (5 papers, 2019 to 2024). A disorder resulting from loss of function or tissue destruction of an organ or multiple organs, arising from humoral or cellular immune responses of the individual to their own tissue constituents. "Further studies are consequently needed to clarify how KMO precisely modulates inflammation, innate immunity, and adaptive immunity, especially in patients with autoimmune diseases and chronically infectious diseases." (PMID 35235615, 2022). "KMO activity profoundly influences macrophage functionality and inflammatory responses, thereby affecting the pathogenesis and progression of inflammatory disorders, including neuroinflammation, autoimmune diseases, and atherosclerosis." (PMID 39026250, 2024).
bipolar disorder (5 papers, 2020 to 2026). A disorder of the brain that causes unusual shifts in mood, energy, activity levels and the ability to carry out day-to-day tasks. "A polymorphism in the KMO gene, rs1053230, has previously been identified to be associated with bipolar disorder." (PMID 39596587, 2024). "Furthermore, KMO activity has been studied in bipolar disorder (BD), a reduced KMO gene expression has been described in the prefrontal cortex of patients with BD with psychotic feature compared with BP patients without psychotic traits." (PMID 34202246, 2021).
Dyskinesia (5 papers, 2015 to 2022). A movement disorder which consists of effects including diminished voluntary movements and the presence of involuntary movements. "Prolonged systemic administration of the KMO inhibitor Ro 61–8048 reduced L‐DOPA–induced dyskinesias in 1‐methyl‐4‐phenyl‐1,2,3,6‐tetrahydropyridine (MPTP)–treated monkeys with overt symptoms of parkinsonism." (PMID 34862742, 2022). "The KMO inhibitors, such as Ro61-8048, have been reported to decrease dyskinesia induced by L-DOPA in monkeys administered with MPTP, with no comprise in the therapeutic role of L-DOPA, as well as elevated production of KYNA." (PMID 34201647, 2021). "The progression of dystonia in hamsters is significantly retarded by KMO inhibitors thus exhibiting its role as potential agents for treating dyskinesia, related to dysfunction of striatum." (PMID 34201647, 2021). "Amplifying KYNA and/or mitigating 3-HK and QUIN, and the use of KMO inhibitor reduced the dystonia and dyskinesia and improved striatal dys-functions through the attenuation of neuroinflammation." (PMID 26712747, 2015). "Additionally, administrated Ro 61-6048, a KMO inhibitor, alleviated dystonia in an animal model, and reduced the levodopa-induced dyskinesia in PD animal model." (PMID 26712747, 2015). "The metabolic arm of KYN is shifted towards KYNA by the action of RO 61-8048, which is a KMO inhibitor, thereby elevating KYNA levels and ameliorating dyskinesia in MPTP monkeys with LID." (PMID 34201647, 2021). "Blockade with 3,4-dimethoxy-N-[4-(3-nitrophenyl)thiazol-2-yl]benzenesulfonamide (Ro-61-8048), a potent KMO inhibitor, results in increased KYNA content in parkinsonian monkeys, and when combined with levodopa, it reduces the severity of dyskinesias, both acutely and after prolonged administration." (PMID 25938971, 2015).
colitis (4 papers, 2023 to 2025). Inflammation of the colon. "Following catabolism by IDO, kynurenine was further catabolized by kynurenine 3-monooxygenase (KMO), and deficiency of KMO led to the accumulation of kynurenine thereby promoting the generation of Tregs to relieve colitis." (PMID 37277776, 2023). "Under the synergistic action of these two aspects, the increase of tight‐junction protein and the reduction of key proteins of tryptophan metabolism such as IDO and KMO regulate cell death caused by inflammation, repair of damaged tissues, and attenuation of colitis." (PMID 39119947, 2024). "Increased levels of Kyn, caused by regulating kynurenine‐3‐monooxygenase (KMO), may contribute to the induction of intestinal T cells and other immune cells during colitis." (PMID 39119947, 2024). "Mice with dextran sulfate sodium (DSS)-induced colitis showed impaired TRP metabolism along with upregulation of KMO and kynureninase (KYNU)." (PMID 39120289, 2024). "Indole metabolites can alleviate colitis; for example, supplementation with indole metabolites such as indole-3-carbinol (I3C), inhibition of kynurenine monooxygenase (KMO), and selective stimulation or inhibition of specific serotonin receptors can mitigate colitis." (PMID 40292216, 2025). "Moreover, blocking KMO with the selective inhibitor Ro 61-8048 alleviated the symptoms of DSS-induced colitis in mice, which was accompanied by an increase in the NAD+ pool and restoration of the redox balance." (PMID 39120289, 2024).
melanoma (4 papers, 2020 to 2022). A malignant, usually aggressive tumor composed of atypical, neoplastic melanocytes. "KMO overexpression is also related to malignancy and poor prognosis in canine mammary gland tumors and melanomas." (PMID 34440798, 2021). "In contrast, KMO expression increases in patients with advanced melanoma who show clinical benefit after PD-1 blockade therapy compared with PD-1-blockade-unresponsive patients; however, the implications of KMO increase in these patients have not been discussed." (PMID 34440798, 2021). "Expression of KMO is not detected in healthy skin, as previously reported or melanoma tumors; while the protein expression of KYNU is lower compared to CCBL1 and CCBL2 both in healthy skin and melanoma tumors." (PMID 32117720, 2020).
Obesity (4 papers, 2016 to 2022). Accumulation of substantial excess body fat. "We have previously shown that the adipose tissue expression of KMO was associated with higher HbA1c in women with obesity and was expressed preferentially in pro-inflammatory M1 macrophages." (PMID 27327770, 2016). "Further linking the pathway to obesity, KYN can then be hydroxylated to 3-hydroxy-l-kynurenine (3OH-KYN) by kynurenine 3-monooxygenase (KMO), which is present in macrophages within adipose tissue but not primary adipocytes." (PMID 34996930, 2022). "In addition to KMO, the enzymes KYNU and KAT may also play a role in the relationship between the kynurenine pathway, obesity and T2D." (PMID 34996930, 2022).
Parkinson disease (4 papers, 2020 to 2022). A progressive degenerative disorder of the central nervous system characterized by loss of dopamine producing neurons in the substantia nigra and the presence of Lewy bodies in the substantia nigra and locus coeruleus. "This implicates KMO in mitochondrial quality control mechanisms which are regulated in part by the familial Parkinson’s disease (PD) associated proteins PINK1 and PRKN." (PMID 33170836, 2020). "Notably, cinnabar genetically interacts with the Parkinson’s disease associated genes Pink1 and parkin, as well as the mitochondrial fission gene Drp1, implicating KMO in mitochondrial dynamics and mitophagy, mechanisms which govern the maintenance of a healthy mitochondrial network." (PMID 33170836, 2020). "In a primate model of MPTP‐induced parkinsonism, orally administered KMO inhibitor, Ro 61–8048, increased central L‐kynurenine and KYNA levels." (PMID 34862742, 2022). "Nonetheless, KMO inhibition still holds promise for treatment of disorders such as Alzheimer’s and Parkinson’s diseases, where amelioration of disease phenotypes has been observed in fruit fly and mouse models of these disorders." (PMID 33750843, 2021). "Given the emerging prominence of aberrant mitochondrial quality control in the pathology of several disorders including Huntington’s, Alzheimer’s and Parkinson’s diseases, we felt it was important to investigate potential mitochondrial functions of KMO, which is localised to the OMM." (PMID 33170836, 2020).
viral myocarditis (4 papers, 2019 to 2024). Myocarditis that is caused by an infection with a viral agent. "One possible connection between acute viral myocarditis and AD is kynurenine 3-monooxygenase (KMO), which is a key regulatory enzyme in the kynurenine metabolism pathway that converts kynurenine to 3-hydroxykynurenine." (PMID 34805976, 2021). "Such interaction may imply a hidden mechanism in AD’s pathogenesis that increases KMO production and thus decreases levels of neuroprotective kynurenine metabolite and enhances AD symptoms, which explains AD’s connection to acute viral myocarditis." (PMID 34805976, 2021).
glaucoma (3 papers, 2021 to 2026). Increased pressure in the eyeball due to obstruction of the outflow of aqueous humor. "The marked elevation of KMO activity in glaucoma patients (p = 0.032) points to a disease-associated shift in tryptophan metabolism toward the production of neurotoxic metabolites." (PMID 40648903, 2025). "We have also recently shown that KMO is overexpressed in two animal models of glaucoma: optic nerve crush and NMDA-induced RGC loss." (PMID 33494373, 2021). "In patients with comorbid glaucoma, heightened KMO activity may synergize with glaucomatous damage by exacerbating RGC loss through oxidative and excitotoxic mechanisms." (PMID 40648903, 2025). "Similarly, glaucoma patients had significantly increased KMO activity (p = 0.032), consistent with enhanced 3-HK-mediated retinal ganglion cell damage." (PMID 40648903, 2025). "The observed increase in KMO activity and the elevated 3-HK/KYNA ratio in patients with glaucoma indicate a potential involvement of KP dysregulation in promoting fibrotic remodeling of the trabecular meshwork." (PMID 40648903, 2025). "The increased KMO activity observed in glaucoma patients suggests enhanced production of neurotoxic metabolites like 3-HK, which could contribute to RGC damage and optic nerve degeneration characteristic of glaucoma." (PMID 40648903, 2025).
ischemic stroke (3 papers, 2018 to 2024). A stroke disorder caused by obstruction of blood flow to the brain, due to thrombotic (local blood clot formation) or embolic (due to a blood clot or other material traveling from another site) event. "Taken together, our analyses indicated that circSCMH1 regulated the KP after ischemic stroke by inhibiting the expression of KMO." (PMID 39659575, 2024). "We found that the overexpression of KMO eliminated the beneficial effects of circSCMH1 on mitophagy and functional recovery after ischemic stroke." (PMID 39659575, 2024). "Together, our results indicated that circSCMH1-mediated decreases in KMO expression inhibited glial activation following ischemic stroke." (PMID 39659575, 2024). "In this study, we explored the mechanism by which KMO is involved in circSCMH1-mediated functional recovery after ischemic stroke." (PMID 39659575, 2024). "The effect of these NMDA receptor effectors makes KMO become an attractive target for the treatment of ischemic stroke." (PMID 32148781, 2020). "The inhibition of kynurenine 3-monooxygenase (KMO) activity reduced brain injury in experimental models of ischemic stroke." (PMID 29963055, 2018). "NMDAR is an important intermediate substrate for KMO treatment of ischemic stroke, and the upstream product IDO of KMO is also a problem worthy of study." (PMID 32148781, 2020).
migraine (3 papers, 2020 to 2024). "The IDO-1, IDO-2, and KMO enzymes and the kynurenine metabolite have been shown to be involved in the pathogenesis of neuropathic pain and other painful conditions (migraine, cluster headache, etc.)as well as depressive behavior." (PMID 32842609, 2020). "In our study, a significantly higher QUIN/KYN ratio was also observed in migraine children, suggesting an increased conversion of KYN to QUINA, which is facilitated by some enzymes, such as kynurenine 3-monooxygenase (KMO), kynurenine lyase (KYNU), and 3-hydroxy anthranilate dioxygenase (HAOO)." (PMID 38177986, 2024).
R6 (3 papers, 2017 to 2022). "Here, we crossed KMO knockout mice to R6/2 HD mice to examine the effect of KMO depletion in the brain and periphery." (PMID 33750843, 2021). "As KMO and QUIN production showed cell type specific expression in microglia, chronic administration of KMO inhibitor JM6 was shown to prevent synaptic degeneration and increase the survival of R6/2 HD mouse model, which is associated with amelioration of microglial activation." (PMID 28674491, 2017).
Anxiety (2 papers, 2016 to 2021). Intense feelings of nervousness, tension, or panic often arise in response to interpersonal stresses. "Moreover, genetic deletion of kynurenine 3-monooxygenase (KMO) in mice, which causes a shift in KP metabolism leading to a several-fold elevation in brain KYNA levels, results in deficits in contextual memory and increased anxiety." (PMID 33498402, 2021).
astrocytoma (2 papers, 2021 to 2022). "This study showed for the first time that KMO, a critical enzyme of the KP, expressed on microglia in the CNS, is expressed and active in astrocytoma." (PMID 34440798, 2021). "The KMO mRNA expression in tissue samples from patients with neurological diseases was significantly lower compared with patients with astrocytoma (0.13 × 106 ± 0.086 × 106 vs. 140.9 × 106 ± 137.4 × 106; p = 0.03)." (PMID 34440798, 2021). "Moreover, KMO was expressed and active in samples from patients diagnosed with astrocytoma of different grades." (PMID 34440798, 2021). "However, the fact that KMO expression and activity are present in astrocytoma samples could be due to tumor-infiltrating cells, since KMO is highly expressed in immune cells, such as macrophages and monocytes and in CNS microglia." (PMID 34440798, 2021). "In this study, mRNA expression, protein expression, and activity of the enzyme kynurenine monooxygenase (KMO) were analyzed in GBM cell lines (A172, LN-18, U87, U373) and patient-derived astrocytoma samples." (PMID 34440798, 2021). "However, the astrocytoma tissue mainly localized KMO and GFAP in the same cells; furthermore, on some astrocytoma slides, KMO immunofluorescence was found unrelated to GFAP marking, suggesting a contribution to KMO expression in tumor-infiltrated cells (lines 3–10)." (PMID 34440798, 2021).
breast tumor (2 papers, 2025). "KMO has been correlated with poor prognosis and accelerated breast tumor progression." (PMID 39997761, 2025). "Upregulation of KMO increases the level of quinolinic acid, which stimulates NMDA receptors to initiate gene activation and cell proliferation, thereby, promoting breast tumor cell survival." (PMID 40145017, 2025).